JAG1 (jagged canonical Notch ligand 1)
Diseases named in the same sentence as JAG1 in open-access papers (continued):
Sharing a sentence is not in itself a finding about the gene and the disease.
Alagille syndrome (157 papers, 2005 to 2026). "Several days later, the gene panel results with a pathogenic loss of function mutation in Exon 15 of the JAG1 gene (c.1984del (p.Ala662Profs∗81)), consistent with a diagnosis of Alagille syndrome." (PMID 41523698, 2026). "Familial testing confirms a diagnosis of Alagille syndrome in one of her three children when her daughter tests positive for the same pathogenic JAG1 variant at the age of 18." (PMID 41523698, 2026). "Alagille syndrome (ALGS) is a rare multisystem disorder most commonly resulting from pathogenic variants in JAG1 and, less frequently, NOTCH2." (PMID 41961327, 2026). "Alagille syndrome is often characterized due to a loss of function mutation in either the JAG1 or NOTCH pathway." (PMID 41323527, 2026). "In the heart, in situ hybridization studies have demonstrated the expression of JAG1 in the vascular structures of mammalian hearts, which is associated with cardiovascular phenotypes observed in Alagille syndrome (ALGS)." (PMID 40026415, 2025). "In humans, heterozygous loss-of-function mutations of JAG1 are associated with Alagille syndrome, which is characterized by multisystem involvement that includes the heart, liver, kidneys, skeleton, eyes, and distinctive facial features." (PMID 41303336, 2025). "While pathogenic JAG1 variants typically cause Alagille syndrome, recent evidence suggests that even isolated mutations can lead to nonsyndromic aortopathy through impaired SMC differentiation and structural malformations of the outflow tract." (PMID 40981152, 2025). "JAG1 mutations have been associated with Alagille syndrome, causing macular atrophy, and with autosomal dominant familial exudative vitreoretinopathy (FEVR)." (PMID 39858590, 2025). "Patient #4 harboured a pathogenic variant (NM_000214: p.I1028T) in JAG1 gene and was diagnosed with Alagille syndrome, an autosomal dominant genetic disorder characterised by extreme clinical heterogeneity." (PMID 39945383, 2025). "Frameshift mutations in the JAG1 gene cause altered protein synthesis, while deletion of this gene leads to haploinsufficiency, causing Alagille syndrome." (PMID 40004644, 2025). "Alagille syndrome is a genetic disorder caused by mutations in the jagged canonical Notch ligand 1 (JAG1) or in the NOTCH2 receptor." (PMID 39199213, 2024). "Readthrough on a construct encoding the JAG1 R235X mutation causing Alagille syndrome was also stimulated in the presence of +8 R-ASO and G418 or Ser-tRNAUGA." (PMID 39011883, 2024). "Genetic mutations responsible for the impaired cleavage of JAG1 have been found in patients with Alagille syndrome." (PMID 39074091, 2024). "Alagille syndrome (ALGS) is a rare autosomal dominant genetic disease caused by pathogenic variants in two genes: Jagged Canonical Notch Ligand 1 (JAG1) and Notch Receptor 2 (NOTCH2)." (PMID 39202394, 2024). "Notch signaling patterns the cochlear organ of Corti, and individuals with the JAG1/NOTCH2-related genetic disorder Alagille syndrome can thus experience hearing loss." (PMID 39373109, 2024). "The Notch ligand JAG1 along with NOTCH2 is instrumental for bile duct formation, and mutation of JAG1 leads to bile duct paucity in Alagille syndrome in humans." (PMID 39699962, 2024). "Alagille syndrome, caused by variants in JAG1 or NOTCH2, is a well-recognized phenotype characterized by highly penetrant posterior embryotoxon and liver dysfunction along with cardiac and vertebral anomalies." (PMID 37895297, 2023). "WES analysis revealed a JAG1 heterozygous splice variant consistent with a diagnosis of Alagille syndrome." (PMID 36797717, 2023). "Pathogenic allelic variants in JAG1 gene have been also described as causing Alagille syndrome, a rare autosomal dominant disease with characteristic liver, cardiac, eye, vertebral, and facial phenotypes." (PMID 36729644, 2023).
Alagille syndrome (continued). "Both the infant and the mother were diagnosed with Alagille syndrome, both having the same heterozygous JAG1 gene (NM_000214.2) variant (c.1890_1893del, p.Ile630Metfs*112)." (PMID 37667743, 2023). "The Notch ligand Jagged1 is essential for the development of intrahepatic bile ducts, and inhibition of Jagged1-mediated Notch signaling or mutation of JAG1 disrupts biliary development and regeneration and leads to Alagille syndrome." (PMID 36737811, 2023). "The identification of JAG1 variants, linked with Alagille syndrome, in three separate families with a clinical diagnosis of ARA/ARS highlights the overlapping features and high variability of these two phenotypes." (PMID 37895297, 2023). "Mutation analysis of JAG1 in Alagille syndrome patients has shown that mutations occur adjacent to the DSL region of JAG1." (PMID 37781534, 2023). "Alagille syndrome is a rare multifaceted disorder that occurs mostly due to mutations in the JAG1 gene and rarely due to mutations in the NOTCH2 gene." (PMID 37890331, 2023). "Pathogenic variants in JAG1 are known to cause Alagille syndrome (ALGS), a disorder that primarily affects the liver, lung, kidney, and skeleton." (PMID 35819173, 2022). "Several syndromes with associated mouse models such as Char syndrome (TFAP2B) and Alagille syndrome (JAG1) have well‐known associations with PDA." (PMID 34350653, 2022). "Alagille syndrome, caused by rare mutations in JAG1 and NOTCH2, includes failure to thrive within its phenotypic spectrum." (PMID 33682876, 2021). "Currently, approximately 94% of Alagille syndrome patients have variants of JAG1, while 1–2% of patients have NOTCH2." (PMID 34651015, 2021). "In a Mexican population, rs1051415 in the JAG1 gene was associated with Alagille syndrome (OMIM#118450),which presents characteristic facial features including a pointed chin." (PMID 34039391, 2021). "On the other hand, the critical role of JAG1 was supported by the finding that mutations in JAG1 result in humans in a condition called Alagille syndrome, which is characterized by a paucity of IHBDs, as well as abnormalities in other organs." (PMID 34360991, 2021). "JAG1 variants are observed in ∼90% of Alagille syndrome patients whereas NOTCH2 variants account for additional 1–2% of individuals with Alagille syndrome." (PMID 33585486, 2021). "Alagille syndrome is caused by mutations in JAG1 and NOTCH2 with major clinical manifestations in the heart and liver, and characteristic facial features." (PMID 33226994, 2020). "Alagille syndrome is caused by loss-of-function mutations in JAG1 or NOTCH2 and leads to partial or complete biliary atresia." (PMID 33135109, 2020). "One infant was diagnosed with Alagille syndrome with de novo heterozygous mutation (c.532delC) in JAG1." (PMID 32296668, 2020). "Many of the features associated with Alagille syndrome have been recapitulated in heterozygous Jag1 mice, but double heterozygous Jag1 and Notch2 mice more closely approximated the phenotypes seen in humans." (PMID 32161758, 2020). "Alagille syndrome is an autosomal dominant disorder usually caused by pathogenic variants of the JAG1 gene." (PMID 33008311, 2020). "Alagille syndrome is associated with loss-of-function mutations in JAG1, which are found across the extracellular and intracellular domain of the JAG1 protein." (PMID 32092942, 2020). "JAG1 has been associated with Alagille syndrome, which involves cholestasis, cardiac defects, ocular abnormalities, skeletal abnormalities and characteristic faces." (PMID 32883240, 2020). "The importance of Notch haploinsufficiency is underscored in studies of Alagille syndrome, which can be caused by heterozygous mutations in either JAG1 or NOTCH2." (PMID 32161758, 2020). "Of note, a human clinical condition with autosomal dominant heritability, termed Alagille syndrome, involves both major frameshift mutations of JAG1 gene and systemic arterial hypertension." (PMID 31686456, 2019).
Alagille syndrome (continued). "Mutations in JAG1 or Notch2 are known causes of Alagille syndrome, an autosomal dominant disease characterized by congenital cholangiopathy with jaundice and bile duct paucity." (PMID 30643196, 2019). "This work demonstrates a novel pathogenic heterozygous JAG1 mutation is associated with an atypical form of Alagille syndrome, suggesting an increased risk for neural tube defects compared to other Alagille patients." (PMID 31835735, 2019). "NGS of high C-triol infants identified three patients with mutations in JAG1 (Alagille syndrome) and ABCB11 (Byler disease) genes." (PMID 31296176, 2019). "In conclusion, this report widens the spectrum of JAG1 gene mutations associated with Alagille syndrome." (PMID 30046498, 2018). "In patients with Alagille syndrome, mutations in the ligand JAG1 or receptor NOTCH2 are associated with bile duct paucity and cholestasis." (PMID 30589410, 2018). "Impaired Notch signalling due to JAGGED1 (JAG1) or NOTCH2 mutations causes Alagille Syndrome, a disease that manifests in the liver by a reduction of bile ducts in combination with cholestasis." (PMID 29990377, 2018). "Here we describe a patient having a new JAG1 mutation associated with early onset and severe Alagille syndrome." (PMID 30046498, 2018). "Heterozygous mutations in JAG1 contributed to the pathogenesis of Alagille syndrome (AGS), TOF, and peripheral pulmonary stenosis (PPS)." (PMID 28372585, 2017). "Mutations in GATA6 cause PTA and haploinsufficiency of JAG1 (a Gata6 target detected in this study) causes Alagille syndrome, a congenital disorder associated with OFT and great vessels defects." (PMID 28952437, 2017). "JAG1 has also been implicated as an important factor in normal human skeletal development and homoeostasis, with Alagille syndrome, a disease characterized by skeletal abnormalities among other symptoms, caused by a JAG1 gene microdeletion." (PMID 27957826, 2017). "Haploinsufficiency at the locus encoding the Notch ligand JAG1 results in Alagille syndrome characterised by impaired intrahepatic bile duct development and widespread ductular reaction." (PMID 28157201, 2017). "The frequency of identifiable genetic mutations in patients with a clinically consistent diagnosis of Alagille syndrome is high, with JAG1 mutations identified in 94% and Notch2 mutations in 2% of affected individuals." (PMID 27855169, 2016). "Patients with Alagille syndrome, in which JAG1 mutations result in a multisystem disorder, can exhibit altered Th1 responses, implicating JAG1 induced signaling in T cell differentiation." (PMID 27532668, 2016). "In conclusion, JAG1 mutations are present in the majority of Chinese pediatric patients with clinical features of Alagille syndrome, and the mutations concentrate on different exons from other reports." (PMID 26076142, 2015). "All “biliary atresia” carriers of JAG1 null mutations developed typical Alagille syndrome at the age of three years." (PMID 26618708, 2015). "Alagille syndrome is an autosomal dominant disorder that results from defects in the Notch signaling pathway, which is most frequently due to JAG1 mutations." (PMID 26076142, 2015). "In humans, mutations in the JAG1 gene cause the Alagille syndrome, characterized by severe cardiac malformation and developmental anomalies in several organs, including kidney." (PMID 24608967, 2014). "The importance of Notch in liver development and hepatocyte differentiation is apparent in the mutation in the Notch ligand Jag1, which is associated with Alagille syndrome, presenting with aberrant bile duct development." (PMID 25551829, 2014). "It has been shown that patients with Alagille syndrome, caused by mutations in JAG1 or NOTCH2, develop calcific AVD." (PMID 29552567, 2014). "Mutations in JAG1, encoding a ligand in the Notch signaling pathway, are found in 95% of patients meeting clinical criteria for Alagille syndrome." (PMID 24391948, 2013).
Alagille syndrome (continued). "With a prior JAG1 mutation positive diagnosis of Alagille syndrome, he presented to the hospital with a subacute, predominantly respiratory febrile condition, eventually diagnosed as sarcoidosis." (PMID 22937766, 2012). "The role of the Notch signaling proteins is not well understood, but is highly conserved; JAG1 is on chromosome 20 and accounts for 70% of the gene mutations in Alagille syndrome." (PMID 22937766, 2012). "Although this is the first published report of sarcoidosis and Alagille syndrome in the same child, a JAG1 mutation would seem to predispose a patient to immunologic dysregulation and the development of granulomas." (PMID 22937766, 2012). "Several forms of CHDs are known to have a genetic basis such as microdeletions (22q11) in DiGeorge Syndrome and single gene mutations (JAG1) in Alagille Syndrome." (PMID 19156209, 2009). "Mice heterozygous for a Jag1 null allele, which have the same genotype as Alagille syndrome patients, exhibited haploinsufficient eye defects but did not exhibit other phenotypic abnormalities characteristic for Alagille syndrome." (PMID 18365007, 2008). "For example the Alagille syndrome is an autosomal dominant disorder associated with mutations or deletions of Jag1 gene or, in less than 1% of cases, with Notch2 mutations." (PMID 19936191, 2008). "We described previously that mice doubly heterozygous for Jag1 and Notch2 mutations are an excellent model for Alagille syndrome." (PMID 18365007, 2008). "Mutations in the JAG1 gene, which encodes a ligand for Notch family receptors, cause Alagille syndrome." (PMID 18365007, 2008). "Recently, heterozygous NOTCH2 mutations were identified in a subset of Alagille syndrome patients who lack JAG1 mutations." (PMID 18365007, 2008). "Alagille syndrome exhibits autosomal dominant inheritance, and analysis of the types of JAG1 mutations in Alagille syndrome patients suggest JAG1 haploinsufficiency as the primary cause of Alagille syndrome." (PMID 18365007, 2008). "Alagille Syndrome (AGS) is a systemic disease caused by heterozygous mutations in the Jagged 1 gene (JAG1) or Notch2 gene (NOTCH2)." (PMID 18937870, 2008). "Alagille syndrome is a developmental disorder caused predominantly by mutations in the Jagged1 (JAG1) gene, which encodes a ligand for Notch family receptors." (PMID 18365007, 2008). "Evidence for genetically heterogeneous etiologies of vertebral malformations includes the identification of mutations in DLL3 in patients with spondylocostal dysostosis and mutations identified in JAG 1 in patients with Alagille syndrome." (PMID 17888180, 2007). "Of note, 75% of Alagille syndrome-causing mutations in JAG1 are the result of frameshift, nonsense, or splice-site alterations, suggesting that a possible mechanism of the disease is JAG1 haploinsufficiency, achieved in vitro by pharmacological inhibition of Notch." (PMID 40691416, 2025). "Alagille syndrome, characterized by multisystem involvement affecting the heart, liver, kidneys, skeleton, and eyes, has been associated with heterozygous loss-of-function mutations of JAG1." (PMID 41303336, 2025). "While JAG1 variants are classically associated with Alagille syndrome, isolated cases of thoracic aortic aneurysm have been observed even in the absence of syndromic features, suggesting that impaired Notch signaling may destabilize arterial structure." (PMID 40981152, 2025). "Alagille syndrome is caused by mutations in JAG1 on chromosome 20 or NOTCH2 on chromosome 1." (PMID 37101309, 2023). "Notch-associated disorders include different types of severe disorders such as Alagille syndrome caused by mutations in both ligand JAG1 and receptor Notch2 and autosomal recessive spondylocostal dysostosis, caused by mutations in ligand DLL3, and many other members of the Notch-signaling pathway." (PMID 36506336, 2022). "The second most frequent disease was Alagille syndrome (AS), which is caused by a JAG1 mutation." (PMID 33763395, 2021).
Alagille syndrome (continued). "Additionally, Alagille syndrome, an autosomal dominant multisystem disorder, is another disorder caused by a mutation in the JAG1 gene." (PMID 34677194, 2021). "This region encompasses the JAG1, mutations in which are associated with Alagille syndrome." (PMID 32277595, 2020). "Interestingly, the combined heterozygous inactivation of Jag1 and a hypomorphic Notch2 allele in mice recapitulated Alagille syndrome." (PMID 32092942, 2020). "The current report widens the spectrum of JAG1 gene mutations associated with Alagille syndrome." (PMID 30046498, 2018). "Recently, anatomic thyroid defects have been found in a series of patients with heterozygous JAG1 variants, including both patients with classical Alagille syndrome (a multisystem disorder known to be caused by JAG1 mutations) and patients with congenital hypothyroidism without syndromic features." (PMID 29026407, 2017). "Mutations in JAG1 found in patients with biliary atresia and Alagille syndrome." (PMID 26618708, 2015). "Rapid testing for JAG1 mutations could prevent misdiagnosis of Alagille syndrome in early infancy and improve their outcome." (PMID 26618708, 2015). "This study investigated the rate, spectrum, and origin of JAG1 mutations in 91 Chinese children presenting with at least two clinical features of Alagille syndrome (cholestasis, heart murmur, skeletal abnormalities, ocular abnormalities, characteristic facial features, and renal abnormalities)." (PMID 26076142, 2015). "The diagnosis was later confirmed by gene sequencing revealing that the patient had a novel G to A point mutation in exon 20 of JAG1, which changes a tryptophan to a premature stop codon, a genetic result that would be consistent with the clinical diagnosis of Alagille syndrome." (PMID 22937766, 2012). "Whereas Alagille syndrome is a well characterized condition mainly caused by haploinsufficiency of JAG1 gene, with manifestations that can range from slight clinical findings to major symptoms in different domains, the 2q31.2q32.3 deletion syndrome is still being delineated." (PMID 22550961, 2012). "Thus, JAG1 mutations, like those seen in Alagille syndrome, are likely to alter T cell development within the thymus and modify effector CD4 T cell differentiation in the peripheral lymphoid organs." (PMID 22937766, 2012). "However, mice doubly heterozygous for a Jag1 null allele and a Notch2 hypomorphic allele exhibited most of the clinically relevant features of Alagille syndrome, including bile duct paucity." (PMID 18365007, 2008). "Moreover, disruption of Notch signaling via mutation in the Notch ligand JAG1 is known to result in Alagille syndrome, nonsyndromic Tetralogy of Fallot (TOF) and possibly nonsyndromic biliary extrahepatic atresia." (PMID 15710038, 2005). "Similarly, JAG1, encoding a Notch ligand, is best known for its role in Alagille syndrome, but recent data suggest that individuals with JAG1 variants may also harbor isolated aneurysmal disease without overt syndromic features." (PMID 40981152, 2025). "In addition to the drosophila studies, missense mutant of Jagged1 induces Nodder and Slalom in mice and, in Human, mutations in DSL and EGF-like repeats domains of JAG1 cause Alagille syndrome and mutations in only EGF-like repeats cause familial tetralogy of Fallot." (PMID 35422684, 2022). "Deleting Jagged1 in the cranial neural crest (CNC) causes (Wnt1-cre, Jag1 Flox/Flox) mice die at postnatal day 30 due to an inability to masticate, owing to jaw misalignment and poor occlusion, recapitulating the midfacial hypoplasia phenotype of Alagille syndrome." (PMID 34039391, 2021). "In addition to liver histology, mutational analysis of JAG1 could be useful for diagnosis of the “grey zone”patients with Alagille syndrome presenting initially as biliary atresia in early infancy." (PMID 26618708, 2015).